RNU7-154P (RNA, U7 small nuclear 154 pseudogene)
Gene: Small nuclear RNA gene on chromosome 7 (122,081,720 to 122,081,781, forward strand). Ensembl gene ENSG00000252003.
Homologues: Orthologues: chimpanzee U7 (97% identical), macaque U7 (90% identical), pig U7 (79% identical). Paralogues in human: RNU7-124P (85% identical), U7 (84% identical), RNU7-160P (82% identical), RNU7-35P (82% identical), RNU7-60P (82% identical), RNU7-97P (82% identical), U7 (82% identical), RNU7-143P (81% identical), RNU7-24P (81% identical), RNU7-52P (81% identical), RNU7-7P (81% identical), RNU7-11P (79% identical), and 143 more.